CHAT (choline O-acetyltransferase)
Diseases named in the same sentence as CHAT in open-access papers (continued):
Sharing a sentence is not in itself a finding about the gene and the disease.
Constipation (2 papers, 2023 to 2024). Infrequent or difficult evacuation of feces. "Notably, attenuated cholinergic function (i.e., impairment of ChAT and acetylcholine release) was associated with constipation by impairing the electrical circuit involved in motility." (PMID 39404390, 2024). "Our results showed that in Loperamide induced constipation, the expression of ChAT protein as well as the number of ChAT positive cells in muscularis propria of colon tissue were diminished." (PMID 37332864, 2023).
Dementia with Lewy Bodies (2 papers, 2017 to 2020). "Post mortem tissue from patients with the Lewy body variant of AD (dementia with Lewy bodies) also show a loss of cholinergic neurons and reduced ChAT activity very early in the disease course." (PMID 32887382, 2020).
developmental delay (2 papers, 2022 to 2023). "ChAT is also expressed at the cholinergic synapses in the CNS, and developmental delay that is observed in about half of CHAT-CMS patients can be accounted for either by defects in the cholinergic synapse in the CNS or by hypoxia due to episodic apnea." (PMID 36835142, 2023). "A hemiallelic large scale DNA rearrangement at 10q11.2 including CHAT and SLC18A3 was observed in 41 patients with autism, developmental delay and/or intellectual disability, and multiple congenital malformations." (PMID 36835142, 2023).
endotoxemia (2 papers, 2017 to 2023). "Furthermore, ACh produced by ChAT+ B cells has been shown to reduce peritoneal neutrophil recruitment during sterile endotoxemia, suggesting the role for B cell-derived ACh in the regulation of innate immunity." (PMID 28932225, 2017).
gastric cancer (2 papers, 2017 to 2023). A primary or metastatic malignant neoplasm involving the stomach. "Firstly, we determined whether ChAT, the rate-limiting enzyme that synthesize ACh, were expressed in different human gastric cancer cell lines and normal gastric epithelial cells." (PMID 28102288, 2017). "Together, these data indicated that the gastric cancer cells could synthesize and secret ACh through ChAT." (PMID 28102288, 2017). "ChAT protein was differentially expressed in human gastric cell lines, it was strongly expressed in MKN28, MKN45, BGC823, MGC803, and SGC7901 gastric cancer cells, while weak positive in normal gastric epithelial cells (GES-1)." (PMID 28102288, 2017).
gastroparesis (2 papers, 2019 to 2021). Paralysis of the muscles of the stomach wall resulting in delayed emptying of the gastric contents into the small intestine. "We previously reported that 6-OHDA rats exhibit gastroparesis, accompanied by a reduction in ChAT and ACh levels in the DMV and gastric muscularis." (PMID 34880768, 2021).
Hypoglycemia (2 papers, 2010 to 2024). A decreased concentration of glucose in the blood. "While hypoglycemia counter-regulation was unaffected in the Trpc5fx/0;ChAT-Cre+ animals, the male and female Trpc5fx/0;DBH-Cre+ mice exhibited more severe hypoglycemia paralleled by significantly lower plasma adrenaline levels." (PMID 39375537, 2024). "In the present study, enhanced muscarinic M1 and M3 receptor binding in the cerebellum of insulin induced hypoglycemia in both diabetic and nondiabetic rats along with increased AchE activity and decreased ChAT expression shows altered acetylcholine metabolism in the cerebellum." (PMID 20137086, 2010).
infarction (2 papers, 2012 to 2016). A localised pathological necrosis of tissue resulting from obstruction of the blood supply usually by a thrombus, an embolus, or vascular torsion. "This local effect also remotely influenced the heart to upregulate ChAT and CHT1 expression as well as ACh and ATP levels in the heart compared with the baseline levels, and more intact cardiomyocytes were spared by this remote effect as evidenced by reduced infarction size." (PMID 23209825, 2012).
influenza infection (2 papers, 2024 to 2025). "Early control of virus replication and IM activation by ChAT B cells affected the course of influenza infection." (PMID 40263611, 2025). "A role for B cell-derived ACh was revealed after influenza infection when viral loads were assessed in mice with a B cell-specific deletion of ChAT (mb-1Cre+/−ChATfl/fl mice, ChatBKO)." (PMID 40263611, 2025). "In further support of direct B cell – IMs interaction, confocal microscopy revealed the co-localization of B220 (CD45R) + B cells and F4/80 + macrophages in the lung interstitium of ChAT-GFP reporter mice at 1 dpi with influenza." (PMID 38978583, 2024). "Thus, ChAT+ B cells seem to be recruited preferentially to F4/80+ macrophages, a response that seems to be enhanced after influenza infection." (PMID 40263611, 2025). "However, it is consistent with the prevalence of ChAT-expressing leukocytes in the respiratory tract, spleen and MedLNs, both at steady state and at 24 h after influenza infection." (PMID 40263611, 2025). "However, this is consistent with the finding that most ChAT-expressing leukocytes are B cells in the respiratory tract, spleen, and MedLN both at steady state and at 24hours after influenza infection." (PMID 38978583, 2024). "If primed and activated ChAT + T cells affect immune responses to influenza infection via ACh release, they would not do so until later timepoints." (PMID 38978583, 2024). "Thus, ChAT B cells modulate the activation and inflammatory cytokine elaboration of lung IMs but not AMs early during influenza infection." (PMID 40263611, 2025).
Insulin resistance (2 papers, 2019 to 2021). Increased resistance towards insulin, that is, diminished effectiveness of insulin in reducing blood glucose levels. "We found that exercise significantly improves HFD-induced glucose intolerance and insulin resistance, along with an increase in acetylcholine level, ChAT activity, and PKC activity, and decrease in TNF-α level in the system and the spleen from HFD-fed mice." (PMID 34717724, 2021). "Noteworthy, NGF sustained the level of ChAT, a cholinergic marker affected by insulin resistance, possibly by ChAT stabilization, exerting further neuroprotective action for BFCN in AD-like neurodegeneration." (PMID 29736736, 2019). "We also demonstrated that subdiaphragmatic vagus nerve amputation eliminated the beneficial effects of exercise training on splenic TNF-α levels, acetylcholine concentration, and ChAT activity and prevented exercise from improving insulin resistance in HFD mice." (PMID 34717724, 2021). "However, sVNS abolished the beneficial effect of exercise on glucose intolerance and insulin resistance, decreased acetylcholine level, ChAT activity, and PKC activity, and increase TNF-α level of the spleen in HFD-mice exercise intervention." (PMID 34717724, 2021).
memory (2 papers, 2020 to 2022). The activities involved in the mental information processing system that receives (registers), modifies, stores, and retrieves informational stimuli. "Scopolamine can produce similar memory deficits seen in the elderly and significantly increase AChE activity and decrease the choline acetyltransferase (ChAT), ACh level and the activities of antioxidant enzymes in the brain of memory-impaired mice." (PMID 32252285, 2020).
neuropathy (2 papers, 2015 to 2023). A disorder affecting the nervous system that manifests with pain, tingling, numbness, and/or muscle weakness. "Thus, although both BM-MSCs and AT-MSCs were effective in attenuating neuronal loss and changes in nNOS and ChAT immunoreactivity, AT-MSCs were less efficacious compared to BM-MSCs in treating neuropathy." (PMID 26652292, 2015). "Moreover, the therapeutic potential of temocapril has been reported in MND such as ALS and neuropathy, through its neurotrophic activity via increase in choline acetyltransferase (ChAT) activity and neurite outgrowth." (PMID 36982902, 2023). "However, AT-MSCs appeared less effective in the attenuation of plexitis, neuropathy, and reduction in ChAT immunoreactivity." (PMID 26652292, 2015).
nicotine dependence (2 papers, 2014 to 2020). Physical and psychological dependence on nicotine. "Although the present study is the first study to describe AIE-induced reductions of ChAT in the medial habenula and interpeduncular nuclei of young adult rats (P80), nicotine dependence is associated with degeneration of this pathway." (PMID 25405505, 2014).
pancreatitis (2 papers, 2022 to 2023). Inflammation of the pancreas. "Therefore, in this study, we established the L-ornithine-induced pancreatitis model in rats in order to examine the changes in ChAT-immunoreactive (ChAT-IR) neurons in myenteric ganglia." (PMID 36317104, 2022). "Together these results of these experiments demonstrate that galantamine mediates its protective effects in caerulein-induced pancreatitis independent of vagus nerve signaling, ChAT+ T cells and nAChRs." (PMID 37907853, 2023). "Galantamine significantly suppressed serum amylase levels and increased serum IL-10 levels in both WT and CD4+/ChATfl/fl mice receiving cerulein, indicating that ChAT expressing T-cells are not required for the protective effects of galantamine in pancreatitis." (PMID 37907853, 2023).
Tourette syndrome (2 papers, 2018 to 2023). A neurologic disorder caused by defective metabolism of the neurotransmitters in the brain. "Recently, it has been demonstrated that ChAT interneurons of the lateral striatum are involved in the development of some of the symptoms of Tourette syndrome, supporting the concept of different subpopulations of ChAT cells." (PMID 30157254, 2018). "It is interesting to note that the striatal changes observed in TgRln mice are opposite to those found in patients with Tourette’s syndrome which present a clear decrease in the density of PV+ and ChAT+ interneurons in the DS with no alterations in the density and number of MSNs." (PMID 37153634, 2023).
Ach (1 paper, 2017). "Acetylcholine (ACh) is a vital neurotransmitter in the brain, the abnormal activity of choline acetyltransferase (ChAT) and acetylcholinesterase (AChE) can cause Ach metabolic disorders, leading to biochemical changes in the central cholinergic nervous system." (PMID 29344413, 2017).
Adult onset (1 paper, 2018). Onset of disease manifestations in adulthood, defined here as at the age of 16 years or later. "However, although these other molecules have also shown the capability to prevent the downregulation in ChAT, or other aspects of motoneuron physiology, their lack does not cause adult-onset ALS-like motoneuron degeneration and paralysis in mice, as happens for VEGF." (PMID 30050409, 2018).
alcoholics (1 paper, 2014). "Reductions of ChAT in these regions may increase the risk for development of alcoholism and other drug dependence." (PMID 25405505, 2014). "Thus, AIE-induced reductions of ChAT+IR in the basal forebrain may contribute to persistent behavioral flexibility deficits and olfaction in adults and adult alcoholics following adolescent binge drinking." (PMID 25405505, 2014).
Anosmia (1 paper, 2026). An inability to perceive odors. "Third, anosmia is also consistent with the virus-mediated secretion of small molecules/peptides affecting the Choline AcetylTransferase (ChAT)-expressing neurons located in the OBs and receiving axons from the magnocellular nuclei of the basal forebrain of cortical areas." (PMID 41597249, 2026).
autonomic dysfunction (1 paper, 2025). "Immunofluorescence staining revealed that autonomic dysfunction in AR mice was ameliorated by minocycline, as evidenced by the up-regulation of TH and NPY and down-regulation of ChAT and VIP in the nasal mucosa." (PMID 41019284, 2025). "Immunofluorescence staining revealed that autonomic dysfunction in AR mice was ameliorated by IL-4 NAb, as evidenced by the up-regulation of TH and NPY and down-regulation of ChAT and VIP in the nose." (PMID 41019284, 2025).
Bradycardia (1 paper, 2023). A slower than normal heart rate (in adults, slower than 60 beats per minute). "Thus, exposure of the DMN to 473 nm light activates cholinergic neurons and induces bradycardia in ChAT-Cre/ChR2-eYFP mice." (PMID 37180135, 2023).
brain trauma (1 paper, 2025). "As ChAT is involved in the synthesis of acetylcholine, a crucial spinal cord neurotransmitter, these results support the hypothesis of cholinergic dysregulation after brain trauma." (PMID 39857801, 2025).
Cachexia (1 paper, 2016). Severe weight loss, wasting of muscle, loss of appetite, and general debility related to a chronic disease. "Therefore, in the current study the decrease in neuronal density of the pan neuronal population (HuC/D-IR) and ChAT-IR and VIP-IR subpopulations may result from systemic effects of cachexia, mediated by oxidative stress." (PMID 27635657, 2016).
carcinoid (1 paper, 2015). "A total of eight of the 18 lung tumors exhibited a significant increase in the mRNA and protein expression of ChoK and ChAT, including four adenocarcinomas, two squamous cell carcinomas, one atypical carcinoid and one small cell carcinoma." (PMID 25591716, 2015).
Cerebellar atrophy (1 paper, 2012). Cerebellar atrophy is defined as a cerebellum with initially normal structures, in a posterior fossa with normal size, which displays enlarged fissures (interfolial spaces) in comparison to the foliae secondary to loss of tissue. "Corresponding with the ethanol-associated motor impairments, cerebellar atrophy, cell loss in Purkinje and granule cell cortical layers, and irregular structure of the subcortical white matter, Hu, MAG-1, and ChAT mRNA levels were significantly reduced in the ethanol-exposed cerebella." (PMID 26322248, 2012).
Cerebral atrophy (1 paper, 2012). Atrophy (wasting, decrease in size of cells or tissue) affecting the cerebrum. "We observe a relationship between cerebral atrophy and ChAT protein and this may reflect the loss of cholinergic neurons known to occur early in disease process." (PMID 23113945, 2012).
cervical cancer (1 paper, 2023). A primary or metastatic malignant neoplasm involving the cervix. "In total, 28 genes (e.g., ATF2, BRCA2, CSRP2BP and EP300) were up-regulated and 16 genes (e.g., CDY1, CHAT and CRAT) were down-regulated in cervical cancer." (PMID 37845756, 2023).
delirium (1 paper, 2021). A disorder characterized by confusion; inattentiveness; disorientation; illusions; hallucinations; agitation; and in some instances autonomic nervous system overactivity. "Moreover, since there is good evidence that cholinergic hypoactivity might be involved in cognitive dysfunction during delirium, we investigated the expression of ChAT-positive neurons in the medial septum and hippocampus (CA1 and CA3 regions)." (PMID 32051550, 2021).
Dyskinesia (1 paper, 2023). A movement disorder which consists of effects including diminished voluntary movements and the presence of involuntary movements. "Restoration of CDK5 expression in striatal cholinergic neurons reduced dyskinesia-like behaviors in ChAT-Cre;Cdk5f/f mice." (PMID 37223477, 2023). "The therapeutic relevance of our findings is highlighted by the amelioration of dyskinesia-like behaviors after local restoration of CDK5 in ChAT-Cre;Cdk5f/f mice." (PMID 37223477, 2023).
Dystonia (1 paper, 2018). An abnormally increased muscular tone that causes fixed abnormal postures. "Based on recent findings showing that the somata of striatal ChAT-positive interneurons are slightly larger in a DYT-1 knock-in mouse model of dystonia than in WT mice, we compared the perikarya volume of ChIs between DRD and WT mice." (PMID 29997483, 2018).
esophageal cancer (1 paper, 2024). A primary or metastatic malignant neoplasm involving the esophagus. "The axes formed by choline O-acetyltransferase (CHAT) and muscarinic receptors CHRM1, 3, and 5 are associated with lower survival in multiple cancers, including liver and esophageal cancer." (PMID 38723607, 2024).
experimental autoimmune encephalomyelitis (1 paper, 2021). An autoimmune demyelinating disease of the central nervous system that is produced experimentally in animals by the injection of homogenized brain or spinal cord in Freund's adjuvant. "Adoptive transfer of ChAT-expressing NK cells (ChAT+ NK cells) into the cerebral ventricles of CX3CR1−/− mice reduces inflammation and autoimmune responses in the experimental autoimmune encephalomyelitis (EAE) model." (PMID 33936095, 2021).
fibrosis (1 paper, 2021). the formation of excess fibrous connective tissue in an organ or tissue in a reparative or reactive process. "Overall, the results revealed, differences in NNCS components in diabetic hearts (human and mice) and sustained cardiac and vascular function and reduced cardiac fibrosis in db/db-ChAT-tg mice compared to the db/db mice." (PMID 33618724, 2021). "As a consequence, db/db-ChAT-tg mice exhibited preserved coronary macro- and microvasculature, reduced cardiac fibrosis and increased cardiac glucose content, overall resulting in improved cardiovascular function in the diabetic heart." (PMID 33618724, 2021).
fluorosis (1 paper, 2023). "Furthermore, our results indicated that the changes in learning, memory, and cognitive function of the fluorosis rats were related to AchE and ChAT activity and were influenced by the fluoride exposure dose." (PMID 37711250, 2023).
food allergy (1 paper, 2022). Gastrointestinal disturbances, skin eruptions, or shock due to allergic reactions to allergens in food. "Single-cell RNA sequencing has revealed that expression of Calca, which encodes α-CGRP, is induced in intestinal killer-cell lectin like receptor G1 (KLRG1)-positive ILC2s in a food allergy model, but it is expressed in choline O-acetyltransferase (ChAT)+ sensory neurons in the steady state." (PMID 35707544, 2022).
frontotemporal dementia (1 paper, 2025). Frontotemporal dementia (FTD) comprises a group of neurodegenerative disorders, characterized by progressive changes in behavior, executive dysfunction and language impairment, as a result of degeneration of the medial prefrontal and frontoinsular cortices. "Next, through an open field test, we noted that general activity levels of the ChAT-Cre; Mettl14floxed mice gradually became compromised and their exploratory behavior in a novel environment was reduced, reflecting a motor deficit and a frontotemporal dementia (FTD)-like phenotype." (PMID 40307231, 2025).
gestational diabetes (1 paper, 2025). Carbohydrate intolerance first diagnosed during pregnancy. "Taken together, the rationale for this study is to determine the plausible roles of the ChAT gene in the pathogenicity of gestational diabetes." (PMID 40688037, 2025).
glioma (1 paper, 2019). A benign or malignant brain and spinal cord tumor that arises from glial cells (astrocytes, oligodendrocytes, ependymal cells). "Therefore, immunocytochemical analysis was performed to examine the subtype of glioma cell-converted neurons using specific markers, including vGluT1 (excitatory interneuron marker), GABA (inhibitory interneuron marker) and ChAT (motor neuron marker)." (PMID 31212628, 2019). "Both vGluT1 and GABA -positive neurons could be observed in the ASCL1-mediated glioma cell-to-neuron system, while no ChAT signal was detected in the culture, suggesting that ASCL1 reprogrammed glioma cells into inhibitory/excitatory interneurons but not motor neurons." (PMID 31212628, 2019).
Hepatitis (1 paper, 2020). Inflammation of the liver. "In the present study, we found that hVNS regulates hepatic expression of inflammatory cytokines TNF-α, IL-1β, and IL-6 in Con-A model of hepatitis and also increases the expression of ChAT gene in the DMV neurons." (PMID 33272194, 2020).
hepatocellular carcinoma (1 paper, 2024). A malignant tumor that arises from hepatocytes. "Intriguingly, the association between the expression of muscarinic receptors-CHAT axis with lower survival in hepatocellular carcinoma correlates with the known involvement of acetylcholinesterase, which opposes CHAT function by degrading acetylcholine, and is associated to better prognosis in HCC." (PMID 38723607, 2024).